CHI3L1 (chitinase 3 like 1)
Diseases named in the same sentence as CHI3L1 in open-access papers (continued):
Sharing a sentence is not in itself a finding about the gene and the disease.
brain injury (2 papers, 2017 to 2025). Acute and chronic (see also brain INJURIES, CHRONIC) injuries to the brain, including the cerebral hemispheres, CEREBELLUM, and brain STEM. "While the precise role of CHI3L1 in the CNS remains incompletely understood, its expression patterns and sustained presence at injury sites suggest that it plays a critical role in both the inflammatory and repair responses following brain trauma." (PMID 39827337, 2025). "Other experiments have provided evidence that CHI3L1, GPR68 and IL1A are involved in the response to traumatic brain injury." (PMID 28097054, 2017). "The multifaceted role of CHI3L1 in TBI not only underscores its importance in modulating the brain’s inflammatory response but also highlights it as a promising target for new therapeutic approaches aimed at reducing inflammation and facilitating recovery after brain trauma." (PMID 39827337, 2025).
cerebral malaria (2 papers, 2014 to 2018). A sequestration of Plasmodium falciparum in the brain, which can cause coma and/or seizures. "While CHI3L1 was elevated by day 5 infection in an experimental model of cerebral malaria, genetic disruption of Chi3l1 did not affect inflammatory responses or outcome." (PMID 29448936, 2018). "CHI3L1 was increased in plasma and brain tissue in experimental cerebral malaria, but targeted Chi3l1 deletion did not alter cytokine production or survival in this model." (PMID 25047113, 2014).
cervical squamous cell carcinoma (2 papers, 2010 to 2022). A squamous cell carcinoma arising from the cervical epithelium. "The objective of this study was to detect the expression of Chitinase-3-like protein 1 (CHI3L1) and CD31-labeled microvessel density (MVD) in cervical squamous cell carcinoma (CSCC) and to assess its prognostic impact." (PMID 35761838, 2022).
childhood asthma (2 papers, 2016 to 2025). "It remains unknown if genetic variations in CHI3L1 or cord blood YKL-40 levels assessed at birth in unselected infants are associated with milder forms of childhood asthma." (PMID 27193312, 2016). "A recent study indicated that genetic variations in CHI3L1 modulate circulating YKL-40 via DNA methylation profiles but showed no direct association with childhood asthma." (PMID 41154593, 2025).
chordoma (2 papers, 2009 to 2026). Chordomas are rare malignant tumors arising from embryonic remnants of the notochord in axial skeleton. "Our results demonstrate elevated CHI3L1 expression in chordoma cells relative to notochordal precursors, with comparative analyses revealing higher CHI3L1 expression in the primary tumor relative to recurrent samples." (PMID 41744820, 2026). "Publicly available preliminary RNA sequencing data from the Chordoma Foundation identified chitinase-3-like 1 (CHI3L1), a secreted glycoprotein implicated in immune checkpoint regulation and epithelial-mesenchymal transition (EMT), as a promising candidate for chordoma immunotherapy." (PMID 41744820, 2026). "Future studies are necessary to elucidate the mechanistic role of CHI3L1 in chordoma immune evasion and to explore targeted interventions that may improve patient outcomes in this aggressive cancer." (PMID 41744820, 2026). "Yet, the comprehensive function of CHI3L1 in chordoma immune response remains unclear." (PMID 41744820, 2026).
dengue (2 papers, 2014 to 2020). "DENV-infected people had high levels of CCL5 and chitinase-3-like 1 during acute infection, and livers from fatal dengue patients had increased CCL5 compared to non-dengue control." (PMID 32854687, 2020).
E. coli infection (2 papers, 2018 to 2024). "CHI3L1 gene expression is also increased in mouse MGs following E. coli infection." (PMID 39268542, 2024). "Again, infection status had a marked correlation with IL-8, but not CHI3L1 levels were seen between the four E. coli infection groups." (PMID 29892291, 2018).
ependymoma (2 papers, 2008 to 2023). A WHO grade II, slow growing tumor of children and young adults, usually located intraventricularly. "Immunohistochemical analysis on a large cohort of paediatric ependymoma revealed that CHI3L1 protein expression is associated with necrosis and that members of the S100 family are differentially expressed in clinically relevant subgroups." (PMID 18781180, 2008). "In conclusion, this study provides evidence that S100A6 and S100A4 are differentially expressed in clinically relevant subgroups, and also demonstrates a link between CHI3L1 protein expression and necrosis in intracranial paediatric ependymoma." (PMID 18781180, 2008). "CHI3L1, located on 1q32.1, was the most overexpressed gene in the relapse pair with 1q gain and was also one of the most upregulated genes in ependymoma when compared with ‘normal’ brain." (PMID 18781180, 2008). "Analysis of the effect of de novo 1q gain on gene expression in recurrent ependymoma revealed that CHI3L1 was the most highly expressed gene." (PMID 18781180, 2008). "Using CGH and SAGE profiling we identified CHI3L1 and members of the S100 family as candidate genes in ependymoma." (PMID 18781180, 2008). "Once the tags were ranked based on the difference in tag count between the recurrent sample of pair R1 and the primary, CHI3L1, S100A10 and PSMB4 were revealed as the top three genes upregulated as a consequence of the gain of 1q in recurrent ependymoma." (PMID 18781180, 2008). "Candidates (CHI3L1, S100A10, S100A4, S100A6 and S100A2) were validated using immunohistochemistry on a tissue microarray of 74 paediatric ependymoma." (PMID 18781180, 2008).
gastric adenocarcinoma (2 papers, 2015 to 2024). "To decipher the cellular state and function of macrophages in the process of intestinal-type gastric adenocarcinoma carcinogenesis, we reclustered all of the macrophages into five clusters, including macrophage_IL1B, macrophage_CHI3L1, macrophage_CXCL3, macrophage_IFIT3 and macrophage_FOLR2." (PMID 39702278, 2024).
gastritis (2 papers, 2025). Inflammation of the stomach. "This study highlights CHI3L1 as a key gene in the transition from gastritis to cancer, confirming its role in promoting cancerous behavior through the CD44-β-catenin-c-Myc pathway." (PMID 40108688, 2025). "Given the significant role of CHI3L1 in the progression from gastritis-to-cancer, we conducted an analysis to identify the cell types responsible for its secretion." (PMID 40108688, 2025). "CHI3L1 was pinpointed as the central driver across the gastritis-to-cancer spectrum, with its upregulation, along with CD44, β-catenin, and c-Myc, noted in gastric precancerous lesions." (PMID 40108688, 2025). "To assess the significance of CHI3L1 in the progression from gastritis-to-cancer, we employed a human gastric mucosal tissue microarray to evaluate the expression levels of CHI3L1 across various pathological stages." (PMID 40108688, 2025). "Our study integrated machine learning techniques with dataset analyses pertaining to GC and gastritis-to-cancer transformation, ultimately identifying CHI3L1 as the pivotal driver gene throughout the gastritis-to-cancer continuum." (PMID 40108688, 2025). "Additional results revealed that CHI3L1 might have higher expression in the serum of patients with gastritis and patients with early‐stage GC." (PMID 40084401, 2025). "Collectively, these findings suggest that the four biomarkers, namely, CHI3L1, FCGBP, VSIG2, and TFF2, hold the potential for diagnosing GC, particularly in cases of gastritis and early‐stage GC." (PMID 40084401, 2025).
glaucoma (2 papers, 2021). Increased pressure in the eyeball due to obstruction of the outflow of aqueous humor. "The upregulation of CHI3L1 and integrins in TMSCs as compared to fibroblasts further strengthen their regenerative role in the Tg-MyocY437H glaucoma model, although the CHI3L1 expression in TMSCs is much lower than that in TM cells." (PMID 33506763, 2021). "Analysis of the combined RNA-Seq and ChIP-Seq data showed that the transcription of several of the differentially expressed genes with roles in TM, IOP, and glaucoma, were directly regulated by GLIS1 and included MYOC, LTBP2, CHI3L1, HMGA1, CYP1B1, and LOXL1-4." (PMID 34385434, 2021).
helminth infection (2 papers, 2023 to 2025). "Next, we assessed whether the defective B cell response observed in the Hp-infected Chi3l1-/- mice was limited to the setting of helminth infection." (PMID 37575256, 2023).
intracerebral haemorrhage (2 papers, 2024). "Moreover, the serum Chi3l1 level is also a candidate prognostic biomarker for cerebral amyloid angiopathy-related intracerebral hemorrhage recurrence." (PMID 39769202, 2024). "Intracerebral hemorrhage (ICH) can damage the brain parenchyma, and Chi3l1 is an effective biomarker for evaluating the severity and predicting long-term clinical outcomes of ICH." (PMID 39769202, 2024).
memory impairment (2 papers, 2024 to 2025). "We demonstrated that CHI3L1 deficiency attenuates the development of Aβ-induced memory impairment and neuroinflammation in mice." (PMID 38791588, 2024). "In this study, we found that monoclonal antibody (mAb) therapy targeting CHI3L1 has improved effects on memory impairment and cognitive function in Tg2576 AD mouse model." (PMID 41573517, 2025).
metastatic melanoma (2 papers, 2010 to 2013). A melanoma that has spread from its primary site to another anatomic site. "The present studies add to these observations by demonstrating that Tg Chi3l1/YKL-40 stimulates TGF-β1 in lungs with metastatic melanoma via an IL-13Rα2-dependent mechanism." (PMID 23972995, 2013).
nematode infection (2 papers, 2023 to 2025). "To address whether Chi3l1 also contributes to TH2 responses following nematode infection, we infected Chi3l1-/- mice with Heligmosomoides polygyrus (Hp) and analyzed T cell responses." (PMID 37575256, 2023). "However, the data also suggested that Chi3l1 made by other cell types might also be important for optimal TH2 development following nematode infection." (PMID 41012147, 2025). "Collectively, these data strongly suggest that Chi3l1 expression by both CD4 T cells and the CXCR5+ cDC2 cells promotes TH2 development following nematode infection." (PMID 41012147, 2025).
Onset (2 papers, 2024 to 2025). The age group in which disease manifestations appear. "We identified a selective increase in CHI3L1 transcript levels in early-onset AD (EOAD), particularly among APOE ε4 carriers." (PMID 41425914, 2025). "Peripheral CHI3L1 expression was elevated in individuals with early-onset AD (EOAD), particularly among APOE ε4 carriers (EOAD APOE ε4+, n = 13 vs. EOAD APOE ε4-, n = 8; p = 0.026)." (PMID 41425914, 2025).
oral cancer (2 papers, 2023 to 2025). "There was a notable link found between CHI3L1 polymorphism variants and the risk of oral cancer along with the risk factors such as smoking, betel nut chewing, and alcohol consumption." (PMID 40256126, 2025).
osteomyelitis (2 papers, 2018 to 2024). An acute or chronic inflammation of the bone and its structures due to infection with pyogenic bacteria. "MicroRNAs (miRNAs) have been shown to play a regulatory role in osteogenesis, and miR-24 inhibits the expression of Chi3l1 mRNA by binding to the 3′-untranslated region to attenuate the effects of S. aureus in osteomyelitis." (PMID 39769202, 2024). "As reported, human miR-24 can target CHI3L1 gene in monocytes, thereby modulating S. aureus-induced macrophage polarization, elevating anti-inflammatory factors expression in M2 macrophages and regulating osteomyelitis." (PMID 30258444, 2018). "Chi3l1 can aggravate S. aureus-induced osteomyelitis by mediating osteoblast differentiation and proliferation through the activation of the p38/MAPK and Smad pathways, whereas the inhibition of Chi3l1 contributes to reducing the debilitating effects of S. aureus in this disease." (PMID 39769202, 2024).
Pleural effusion (2 papers, 2015). The presence of an excessive amount of fluid in the pleural cavity. "The metastatic CHI3L1-negative SCLC cell line SCLC26A, established from a pleural effusion was used for comparison." (PMID 26328272, 2015).
polycystic ovarian syndrome (2 papers, 2015 to 2024). "Polycystic ovary syndrome (PCOS), another female reproductive disease, can be characterized by increased Chi3l1 levels." (PMID 39769202, 2024).
schistosomiasis (2 papers, 2012 to 2014). An infectious disease caused by parasitic trematodes of the genus Schistosoma that colonize human blood vessels and release eggs that can cause granulomatous reactions leading to acute (swimmer's itch or acute schistosomiasis syndrome) or chronic disease. "We showed that CHI3L1 is elevated in schistosomiasis infected individuals over uninfected individuals, with the strongest association seen in the youngest age group who have a shorter history of schistosome infection." (PMID 23145202, 2012). "In this study we assessed the levels of CHI3L1 in a group of individuals from a schistosomiasis endemic area in Zimbabwe." (PMID 23145202, 2012).
scleroderma (2 papers, 2022 to 2024). Scleroderma is a rare autoimmune connective tissue disorder characterized by abnormal hardening of the skin and, sometimes, other organs. "Previous studies have identified CHI3L1 as an indicator of disease severity and prognosis in patients with idiopathic PAH, PAH associated with scleroderma, and IPF, but the mechanism of CHI3L1 in the pathogenesis of PH has not been investigated to our knowledge." (PMID 35951428, 2022).
scoliosis (2 papers, 2019 to 2024). A congenital or acquired spinal deformity characterized by lateral curvature of the spine. "We further identified significant associations of multiple CHI3L1 SNPs and their haplotypes with plasma YKL-40 levels and scoliosis severity as a function of their classification in a specific endophenotype." (PMID 30952886, 2019). "We further identified significant associations of multiple CHI3L1 SNPs and their haplotypes with plasma YKL-40 levels and scoliosis severity." (PMID 30952886, 2019).
Streptococcus pneumoniae infection (2 papers, 2014 to 2018). "In line with our current observation in CHI3L1-deficient mice, a Streptococcus pneumoniae infection also induced higher levels of IL-1beta in BAL fluid of CHI3L1−/− compared to CHI3L1+/+ mice." (PMID 29892291, 2018). "Analysis of resistance and tolerance mechanisms is often complicated because some host factors may control and participate simultaneously in both types of responses, as it has been proposed for the enzyme Chi3l1 during Streptococcus pneumoniae infection." (PMID 25166912, 2014).
systemic inflammatory response syndrome (2 papers, 2023 to 2025). SIRS is a serious condition related to systemic inflammation, organ dysfunction, and organ failure. "ATAAD surgery and the use of CPB can induce systemic inflammatory response syndrome that leads to ASA-AKI and the secretion of CHI3L1 might increase during this process." (PMID 38110934, 2023).
ulcer (2 papers, 2022 to 2024). "The analysis of the most enriched gene, CHI3L1, reveals that HE‐Fibro had stronger adhesion ability and lower migration ability, and could anchor on ECM and mediate ulcer healing through secreting molecules." (PMID 39264020, 2024). "The fibroblast population overexpressed in DFU‐healed patients is designated HE‐Fibro, and in‐depth analysis of its subpopulation reveals that high expression of genes related to ECM remodelling (MMP1, MMP3) and immunity/inflammation (CHI3L1, TNFAIP6) is conducive to ulcer wound healing." (PMID 39264020, 2024). "We stained for inflammatory fibroblast markers, CHI3L1 and TIMP1, together with pan-fibroblast marker fibroblast activation protein (FAP) and discovered elevated numbers of triple-positive cells within the ulcer area of healing DFUs, with the cells forming dense aggregates." (PMID 35013299, 2022).
urinary tract infection (2 papers, 2016 to 2023). "This could implicate that in the urine of patients with a urinary tract infection (UTI), CHI3L1 is increased too." (PMID 26864834, 2016).
viral hepatitis (2 papers, 2024). An acute or chronic inflammation of the liver parenchyma caused by viruses. "It is well‐established that acute liver injury, such as viral hepatitis, can induce the activation of hepatic stellate cells and liver macrophages, leading to an increased expression of CHI3L1, lifted AST/ALT levels, and decreased PLT, ultimately resulting in elevated APRI and FIB‐4." (PMID 38380526, 2024).
acute tubular necrosis (1 paper, 2018). "CHI3L1 expression has been reported on the surface of tubular epithelial cells, consistent with either uptake of filtered CHI3L1 or tubular cell secretion, and urinary CHI3L1 levels correlate with the severity of acute tubular necrosis." (PMID 29448936, 2018).
Alexander disease (1 paper, 2019). Alexander disease (AxD) is a rare neurodegenerative disorder of the astrocytes comprised of two clinical forms: AxD Type I and Type II manifesting with various degrees of macrocephaly, spasticity, ataxia and seizures and leading to psychomotor regression and death. "Additionally, high levels of pathological CHI3L1 release have been observed in Alexander disease, a leukodystrophy which results in a dysregulation of myelination, caused by a glial fibrillary acidic protein (GFAP) mutation in astrocytes." (PMID 31561550, 2019).
anaplastic oligodendroglioma (1 paper, 2024). A WHO grade III oligodendroglioma with focal or diffuse malignant morphologic features (prominent nuclear pleomorphism, mitoses, and increased cellularity). "CHI3L1 expression was higher in GBMs compared to anaplastic oligodendrogliomas, and among GBMs, tumors with EGFR amplification or elevated EGFR expression had lower CHI3L1 expression." (PMID 39033204, 2024).
anxiety disorder (1 paper, 2022). A category of psychiatric disorders which are characterized by anxious feelings or fear often accompanied by physical symptoms associated with anxiety. "Considering this, G721-0282 as the inhibitor of CHI3L1 could be used a treatment for anxiety disorders accompanying neuroinflammation." (PMID 35345530, 2022).
Aortic dissection (1 paper, 2025). Aortic dissection refers to a tear in the intimal layer of the aorta causing a separation between the intima and the medial layers of the aorta. "Other novel inflammatory markers were also examined to determine their prognostic value in patients with Type A aortic dissection, such as S100A8/A9, pentraxin 3, chitinase 3-like 1, and S100B." (PMID 39910669, 2025).
atopic allergy (1 paper, 2017). "The genetic polymorphisms of the CHI3L1 promoter are also responsible for the expression of YKL-40, which provides the evidence that this protein contributes to the atopic allergy." (PMID 28660216, 2017).
autoimmune liver diseases (1 paper, 2025). "The results revealed that the serum CHI3L1 levels were significantly higher in patients with autoimmune liver diseases than in the CHB patient group, with median values of 240.27 ng/mL (IQR 132.62 - 426.60) and 118.38 ng/mL (IQR 69.03-168.43), respectively; p<0.001." (PMID 40352927, 2025).
bone resorption disease (1 paper, 2024). A disease that has its basis in the disruption of bone resorption. "Previous studies have identified Chi3l1 as a biomarker in many malignancies and inflammatory diseases, but the role of Chi3l1 in bone resorption diseases was poorly understood." (PMID 38291404, 2024).
bone tumor (1 paper, 2020). "In addition, we demonstrated that Chi3L1 expression was correlated with p-STAT3 level in human bone tumor tissues." (PMID 31929760, 2020). "Furthermore, the anti-tumor effects of G721-0282 were observed in an xenograft in vivo model in association with the reduced expression of Chi3L1, PCNA, Cyclin D1, p-STAT3, as well as the increased expression of Chi3L1 was correlated with the p-STAT3 level in human bone tumor tissues." (PMID 31929760, 2020).